IL6 (interleukin 6)
Diseases named in the same sentence as IL6 in open-access papers (continued):
Sharing a sentence is not in itself a finding about the gene and the disease.
COVID-19 (continued). "In patients with severe COVID-19, higher interleukin (IL)-6, IL-10, granulocyte-colony stimulating factor (G-CSF), monocyte chemoattractant protein 1 (MCP1), macrophage inflammatory protein (MIP)1α, and tumor necrosis factor (TNF)-α were reported." (PMID 34440608, 2021). "When we corrected the condition of hypovitaminosis D in a small group of COVID-19 patients with chronic renal failure by supplementing 1α,25(OH)2D3 for one week, we observed a steep and significant decrease in circulating IL-6 levels." (PMID 34836187, 2021). "The drugs blocking IL-6 receptor (IL-6R), such as tocilizumab, sarilumab and siltuximab, have been considered as a treatment strategy for severe COVID-19 patients with high IL-6 levels." (PMID 34578457, 2021). "Accordingly, in this current study, the aim was to assess the vitamin D, IL-6, and eGFR levels in serum obtained from three different groups of COVID-19 patients." (PMID 34576798, 2021). "Several studies have pointed to a strong correlation between elevated IL-6 (prevalent in cytokine storm) levels in the serum and the development of respiratory failure in COVID-19 patients." (PMID 34452063, 2021). "Severe COVID-19 is characterized by increased blood concentrations of the cytokine interleukin-6 (IL-6) and other inflammatory cytokines." (PMID 34966605, 2021). "In particular, IL-6 directly reduces the expression of perforin and granzyme B. In patients with COVID-19 admitted to the intensive care unit, an inverse correlation between serum levels of IL-6 and NK cells’ frequency of expressing granzyme A was found." (PMID 33669527, 2021). "How should hyperinflammation in COVID-19 be managed and what should be the position of IL-6 inhibitors in the treatment of severely to critically ill patients?" (PMID 34631752, 2021). "Highly increased IL-6 concentrations can be decisive for severe inflammatory conditions in COVID-19." (PMID 33445810, 2021). "A significantly higher proportion of COVID-19 convalescent individuals presented with increased IL-5, IL-6, and IL-1β levels." (PMID 34234102, 2021). "A retrospective study in Italy looked at the clinical impact of hyponatremia and the correlation with IL-6 levels in a group of patients diagnosed with COVID-19." (PMID 33435405, 2021). "The results showed that IL6R/IL6/IL6ST (PDB ID: 1P9M) had high level of CDOCKER interaction energy with the Spike protein of COVID-19 (PDB ID: 6VXX)." (PMID 34731090, 2021). "The median proportion of IL-6 level was higher in critical COVID-19 than sever COVID-19 patients (respectively 10.5 vs. 4.0, p < 0.05), similar tendency was for IL-8 level, but not significant (7.6 vs. 3.9, p > 0.05)." (PMID 34064802, 2021). "Recent studies have shown that impaired response of type-1 IFNs in early stage of COVID-19 infection played a major role in the development of cytokine storm, and various cytokines such as IL-6 and IL-1 were involved in severe COVID-19." (PMID 33391477, 2021). "When we analyzed the median proportion of selected cytokines levels (pg/mL) such as: IL-1β, IL-4, IL-5, IL-6, IL-8, IL-10 and TNFα, we observed significant difference between severe COVID-19 and critical COVID-19 patient only for IL-6 level." (PMID 34064802, 2021). "In data from a different cohort, we also observed an early spike of blood expression of IL-6 in severe COVID-19 illness, which returns, over time, to levels comparable with moderate illness." (PMID 34775962, 2021). "The brain's microstructural changes and CBF in the insula in the severe COVID-19 group were highly correlated with procalcitonin and interleukin-6 inflammatory markers." (PMID 34230916, 2021). "For instance, IL-6, which has been strongly connected to clinical outcomes of COVID-19, appears to be a significant regulator of immunologic and inflammatory reactions in hypertension." (PMID 34806090, 2021).
COVID-19 (continued). "In our study, when analyzing the differences in median levels of cytokines in patients with severe and critical COVID-19, we noticed significant changes only for IL-6 level." (PMID 34064802, 2021). "The IFNα/β response is one of multiple responses, including production of IL-6, TNFα, and IL-1b, by innate and adaptive immune cells that have the potential to limit COVID-19 progression." (PMID 34368185, 2021). "Patients with severe COVID-19 show increased levels of IL-6, IL-8, IL-10, IL-2R, and tumor necrosis factor (TNF)-α compared to those with mild to moderate disease." (PMID 34315546, 2021). "The Chinese Health Commission and the Italian Society for Infectious and Tropical Diseases both had suggested the use of anti-IL-6 monoclonal antibodies (mAbs) such as tocilizumab in COVID-19 treatment." (PMID 35822018, 2021). "The increased systemic values of TNF-α, IL-1β, IL-6, IL-12, IL-23, and IL-33 support the prevalence of innate pro-inflammatory mediators in the serum of subjects with a severe form of COVID-19." (PMID 34917631, 2021). "In our COVID-19 patients, low 25OHD levels were inversely correlated with high IL-6 levels and were independent predictors of COVID-19 severity and mortality." (PMID 34126960, 2021). "The cytokine levels of CXCL-10, GCSF, IL-2 and IL-6 were significantly reduced upon the discharge of severely ill COVID-19 patients." (PMID 34677394, 2021). "In our meta-analysis, the findings clarify the role of ferritin in the assessment of the systemic hyper-inflammation and can explain the relationship between hyperferritinemia and high levels of IL-6 among adult patients with COVID-19." (PMID 34185801, 2021). "Our study is perhaps the first one to evaluate the equivalency between the NLR and the serum levels of IL-6 in the context of COVID-19 severity." (PMID 33819261, 2021). "Serum proteomics of COVID-19 patients has been documented in multiple studies, often stratified by disease severity and comorbidities, representing IL6 concentrations as a marker of disease severity and prognosis." (PMID 35145507, 2021). "To answer this, we assessed NR3C1 and IL-6 expression levels in each recovered BALF cell population between cases of mild COVID-19 (n = 3) and severe COVID-19 (n = 6), along with healthy controls (n = 3)." (PMID 33723251, 2021). "Systemic inflammatory cytokines such as interleukin-6 (IL-6) and tumor necrosis factor-alpha (TNF-α) and specific Th1 cytokines like interferon-induced protein-10 (IP-10) are associated with COVID-19 severity and mortality." (PMID 34938289, 2021). "The present study reported a novel association of SNPs rs1800796, rs1524107, and rs2066992 at the IL-6 locus with COVID-19 severity in a Chinese population." (PMID 34634929, 2021). "Our results highlight the potential of these IL-6 SNPs as biomarkers in the prognosis and treatment of COVID-19 in populations with Asian ancestry." (PMID 34634929, 2021). "They all had p-values < 0.05 in the multivariate model, suggesting an independent prognostic effect of early levels of MYO, NEU, hs-CRP, IL-6, and D-dimer on COVID-19 mortality." (PMID 34458331, 2021). "In this regard, in a meta-analysis study conducted on a total of 1426 COVID-19 patients it has been demonstrated that, mean IL-6 levels were extremely higher in complicated COVID-19 patients in comparison to those with non-complicated disease." (PMID 34895167, 2021). "The other paper reported that COVID-19 patients have lower lymphocyte counts and increased interleukin (e.g., IL-6) and TNF-α levels compared with the healthy cohort." (PMID 34161373, 2021). "These cytokines, such as IL-6, IL-7, CCL-2/MCP-1, CCL-3/CCL-4 MIP-1α/β, TNF-α, and G-CSF, have been implicated in COVID-19 pathogenesis." (PMID 34341347, 2021). "The increased IL-6 in COVID-19 patients can bind to the glycoprotein (gp130) receptor and IL-6 receptor, thereby facilitating the downstream activation of JAK/STAT signaling." (PMID 33995078, 2021).
COVID-19 (continued). "IL-6, which is widely reported to be increased in COVID-19, also directly regulates neutrophil trafficking." (PMID 35593707, 2021). "IL-6-mediated inflammation plays a role in both COVID-19-derived cytokine storm, and cardiometabolic pathologies in the heart, kidney, pancreas and systemic vasculature." (PMID 34178414, 2021). "Adipose tissue increases the production of inflammatory cytokines, such as IL-6, in which its blockade has demonstrated promising results as a COVID-19 therapeutic option." (PMID 34435518, 2021). "The analysis of the immune characteristics of patients with severe COVID-19 revealed significantly upregulated levels of cytokines, including IL-6, TNF-α, IL-1β, and IL-8, among others." (PMID 34360706, 2021). "Our results revealed a stronger positive correlation between serum values of IL-33 and innate immunity mediators TNF-α, IL-1β, IL-6, IL-12, and IL-23 in the severe form of COVID-19." (PMID 34917631, 2021). "The level of serum IL-6 is high in both severe COVID-19 cases and in alloHSCT patients having high grade aGvHD, being predictive of an ominous outcome." (PMID 34149697, 2021). "In a meta-analysis of 86 studies, severe COVID-19 was strongly associated with lymphocytopenia, hyperglycemia, ARDS, and high levels of interleukin (IL)-6 and C-reactive protein (CRP)." (PMID 33530554, 2021). "The concentration of IL-6 is significantly elevated in COVID-19 patients compared with that of healthy individuals, who only exhibited 0–7 pg/mL." (PMID 34205852, 2021). "In the process of COVID-19, elevated plasma levels of IL-6, IFN-γ, IL-2, IL-7, IL-15, G-CSF, MCP1, MIP1α, and TNF were observed." (PMID 34945800, 2021). "Immunomodulatory therapies such as anti-IL-6 have been effective in controlling cytokine storms during COVID-19 and limiting its complications." (PMID 33995033, 2021). "Significantly increased systemic levels of the proinflammatory cytokine IL-6 were reported in several cohorts of COVID-19 patients; the levels of IL-6 correlated with disease severity." (PMID 34603758, 2021). "We also found elevated plasma levels of IFN-γ, IL6, and C-reactive protein in samples from COVID-19 patients." (PMID 35062250, 2021). "Other therapeutics interfering in the IL-6 pathways are also being tested for their efficacy in COVID-19." (PMID 33445810, 2021). "This review documents studies that found decreased T-lymphocytes subsets mainly CD4+ T and CD8+ T cells as well as elevated cytokines such as IL-6 in severe and critically ill COVID-19 patients." (PMID 34287285, 2021). "PPI network for the immunity and inflammation cytokines in COVID-19 among R. crenulata targets showed that IL-10, IL-6, IL-1B, TNF-α, CCL2 and CXCL8 were important nodes in the network." (PMID 34313585, 2021). "Dramatically, over 50% of COVID-19 patients needed respiratory support due to an excessive pro-inflammatory response, with a massive release of interleukins (IL)-1β, IL-6 and Tumor Necrosis Factor (TNF)-α, chemokines and anti-inflammatory cytokines." (PMID 33815368, 2021). "Considering the robust up-regulation of NETosis, complement pathways and transient early rise of IL-6 in severe cases of COVID-19, a model is proposed." (PMID 34775962, 2021). "In comparison with other pulmonary infections, severe COVID-19 is characterized by massive activation of the inflammatory response, which is substantiated in the so-called “cytokine storm” with elevation of IL-6 and TNF-α in blood." (PMID 34326704, 2021). "Correlation analyses are mainly associated with increased levels of IL-6 and CRP and decreased CD4+ cell counts with the severity of COVID-19 in people with diabetes." (PMID 34786431, 2021). "Among these, IP-10, IL-10 and IL-6 have been proposed as a triad predictive of subsequent COVID-19 clinical progression." (PMID 34539631, 2021). "CRP was positively associated with IFNγ, IL-2, TNFα IL-1α IFNβ IL-6 IL-17A IL-10, CXCL-10 and VEGF in children with PIMS-TS and COVID-19." (PMID 33813138, 2021).
COVID-19 (continued). "Increased expressions of IL-6 and granulocyte monocyte colony stimulating factor (GM-CSF) was detected in COVID-19 patients." (PMID 33921113, 2021). "JAK/STAT signalling is also employed by other cytokines such as IL-6; indeed IL-6 is commonly elevated in COVID-19 patients and tightly correlated with disease severity." (PMID 33810391, 2021). "Dysregulation of IL-6 was found to be related to the COVID-19 progression, and previous findings have reported its association with the severity of the disease, respiratory failure, and mortality in this group of patients." (PMID 34895167, 2021). "The purpose of this review is to discuss the potential mechanism of IL-6 during cytokine storms in COVID-19 patients from the perspective of its structure, general function and what we have known about it in COVID-19 pandemic so far." (PMID 37287491, 2021). "IL-6 has been shown to be a key biomarker for severe COVID-19, so there is an alternative method to integrate the common factors regulated by IL-6 from other diseases or treatment studies." (PMID 33520118, 2021). "Of these patients, we considered ten critically ill COVID-19 patients who received IL-6 plasma tests both before and after corticosteroid administration." (PMID 33723251, 2021). "ATX serum levels correlated with the corresponding increased serum levels of IL-6 and endothelial damage biomarkers, suggesting an interplay of the ATX/LPA axis with hyperinflammation and the associated vascular dysfunction in COVID-19." (PMID 34576169, 2021). "This extensive proteomic analysis unbiasedly identified IL6 and five novel proteins (CKAP4, Gal-9, IL-1ra, LILRB4 and PD-L1) to be associated with disease severity in COVID-19 cases." (PMID 33737684, 2021). "The consistency in results provides validity across the different panels and demonstrates that IL6 protein is reliably detected as significantly increased in COVID-19." (PMID 33737684, 2021). "Siltuximab (EUSA Pharma, Hempstead, UK and BeiGene Ltd., Beijing, China) is a chimeric IgG1 targeting IL-6, indicated in patients with multicentric Castleman’s disease and evaluated in Phase 3 in COVID-19 (NCT04330638)." (PMID 33668613, 2021). "Some of the hallmarks of immune aging observed in both sexes, such as the decline in CD8+ naïve T cells and elevated circulating levels of IL-6 and IL-8, are shared with the pathophysiology of severe COVID-19." (PMID 34434199, 2021). "The observed pronounced inhibition of TNFα and IL-6 is the most important finding, because these molecules are currently considered to be the main targets in COVID-19 cytokine storm and ARDS pathogenesis." (PMID 33465050, 2021). "Increased levels of cytokines often occur in critically ill patients with COVID-19, including IL-6, IL-2R, IL-10, and tumor necrosis factor-α." (PMID 34858386, 2021). "IL-8 is one of the cytokines that characterizes the cytokine storm in severe COVID-19 patients; IL-6 is a prominent cytokine also involved in the cytokine storm and is secreted during the disease from alveolar epithelial cells." (PMID 33446817, 2021). "Then we detected the expression of CyPA, macrophage marker CD68, CCL2, and IL-6 in lung tissues from 13 cases of COVID-19 patients using multiplex immunofluorescence." (PMID 34564690, 2021). "Tocilizumab is an mIL-6R and sIL-6R inhibitor that reverses the increases in serum CRP and IL-6 levels in patients with COVID-19." (PMID 33404925, 2021). "Previously, we found that individuals with severe COVID-19 have high systemic levels of IL-6, IL-10, VEGF and sCD40L." (PMID 35082777, 2021). "IL-6 involvement in liver failure during COVID-19 is also established as a part of the cytokine storm." (PMID 34576853, 2021). "Among them, IL-6 and sIL-2R were found to be clinically significant in COVID-19 patients with respiratory failure." (PMID 34575353, 2021). "The severity of COVID-19 is correlated with the levels of interleukin (IL)-6, C-reactive protein (CRP), and other proinflammatory cytokines." (PMID 33029758, 2021).
COVID-19 (continued). "Patients with severe COVID-19 had lower lymphocyte count and higher median values of transaminases, lactate dehydrogenase, C-reactive protein, procalcitonin, D-dimer, and interleukin-6 than patients with mild-to-moderate COVID-19 (all P < 0.001)." (PMID 33481096, 2021). "Plasma levels of IL-6, TNFα, IL-1β, IL-10 and IL-21 were significantly higher in Asymptomatic COVID-19 cases as compared with Controls." (PMID 34824360, 2021). "This study investigated two prognostic biomarkers, the high mobility group box 1 (HMGB1) and interleukin-6 (IL-6), in patients with severe COVID-19 at the time of admission in the intensive care unit (ICU)." (PMID 33939645, 2021). "There was a significant interaction effect between serum IL-6 levels and MAFLD for risk of severe COVID-19 (p for interaction = 0.008)." (PMID 33763027, 2021). "Lymphocyte and platelet counts, as well as interleukin-6 levels, can help predict the mortality of patients with COVID-19." (PMID 34938342, 2021). "A recently published Cochrane Database analysis of IL-6-blocking agents for treating COVID-19 showed that tocilizumab slightly reduced mortality but resulted in little or no clinical outcome improvement." (PMID 34578460, 2021). "This is consistent with the IL-6 signalling pathway, which seems to be involved in the damage produced by COVID-19." (PMID 33472588, 2021). "With the presence of cytokines (TNF-1 and IL-6) and chemokines (IL-8), patients with severe COVID-19 had a higher incidence of structural damage in the body." (PMID 34829418, 2021). "Consistently, the levels of interleukin 6 (IL-6) are increased in severe and critically ill COVID-19 patients, which is thus being considered as the prognostic and predictive disease biomarker along with the numbers of neutrophil/lymphocytes." (PMID 35002711, 2021). "By characterizing subclinical myocardial dysfunction using STE, the present study provides incremental knowledge, linking increased systemic inflammation (by IL-6 levels) to the pathophysiology of myocardial injury and dysfunction in COVID-19." (PMID 34195234, 2021). "Our study highlighted current gaps of knowledge in IL-6 inhibitors use among patients with COVID-19." (PMID 34704175, 2021). "Other scientists have shown that laboratory parameters like increased values of C-reactive protein, interleukin-6, lactate dehydrogenase, and D-Dimer are predictors of mortality in COVID-19." (PMID 34182946, 2021). "It has been revealed that patients with severe COVID-19 present higher levels of IL-2, IL-6, IL-7, IL-10, and TNF-α than the patients with mild and moderate disease." (PMID 34088317, 2021). "Application of cytokine-modulatory therapy, especially anti-IL-6 agents, is expected to improve the prognosis of severe COVID-19." (PMID 33613111, 2021). "An increased level of IL-6 in patients is considered an important predictor of the course of most serious diseases and a need for intensive care among patients infected with COVID-19." (PMID 33692211, 2021). "It seems that the level of IL-6 is the most important here as higher levels of this interleukin were manifested in patients with the severe course of COVID-19." (PMID 34439868, 2021). "A few preliminary clinical studies on vitamin C in critical COVID-19 patients have shown some improvements in the oxygenation and interleukin-6 level, though a lower benefit for the mortality rate has been reported." (PMID 33921297, 2021). "In ex vivo studies, NK cells from patients with COVID-19 displayed impaired cytotoxicity, potentially due to cytokine dysregulation and high plasma levels of interleukin-6 and tumor necrosis factor–α." (PMID 34035118, 2021). "Lymphocyte count was negatively associated with IFNγ, IL-2, TNFα, IL-1α, IFNβ, IL-6, IL-17A, IL-10, CXCL-10 and VEGF in children with PIMS-TS and COVID-19." (PMID 33813138, 2021).